SOX2 (SRY-box transcription factor 2)
Diseases named in the same sentence as SOX2 in open-access papers (continued):
Sharing a sentence is not in itself a finding about the gene and the disease.
cancer (continued). "Compared with monolayer-culture GBM cell lines, cancer stem cell (CSC) markers such as SOX2, PROM1, POU5F1, MSI1, FUT4, and CXCR4 were upregulated in the spheroids." (PMID 34638384, 2021). "In summary, our approach opens the door to personalized cancer treatment by inhibition of SOX2 using iPeps to block protein–protein interfaces between SOX2 and its molecular effectors potentially." (PMID 34502261, 2021). "The cell-fate determining transcription factor SOX2 plays an important role in development, stem cell biology, and cancer, and thus, undergoes situation-specific protein modifications that can affect the nuclear-cytoplasmic localization of the protein." (PMID 34072957, 2021). "The regulation of Sox2 expression is extremely complex and variation of its expression levels has contrasting consequences in cancers." (PMID 33574062, 2021). "Our results revealed that the expression of CK-18 and E-cadherin were downregulated, and the expression of genes related to EMT induction and cancer aggressiveness, including Twist, Snail, SOX2 and Vimentin, were upregulated upon HK2 overexpression." (PMID 34174908, 2021). "The transcription factor SOX2 plays an important role in maintaining the stemness properties and apoptosis resistance of cancer cells 6-9." (PMID 33456560, 2021). "The interplay between Oct-4 and Sox-2 can also form an intricate network for self-renewal modulation in several cancer stem-like cells." (PMID 34903921, 2021). "These excess β-catenin translocated to the nucleus and activated the downstream genes expression, including c-Myc, Sox2, Nanog, Oct4, Survivin and Cyclin D1, thus contributing to oncogenesis and cancer development." (PMID 34257574, 2021). "These ATF3-induced tumors were also found to have reduced expression of Mir145 and Mir143, leading to upregulation of the transcription factors Klf4 and Sox2 and the cancer stem cell-related gene Kras, respectively." (PMID 33652981, 2021). "Additional research from our lab supports YAP1 and COX2 as inducers of cancer stemness via SOX2 upregulation." (PMID 34680249, 2021). "Western blotting was used to detect the expression of cancer stem cell markers Oct4, Bmi1, and Sox2 after the induction of EMT in gliospheres as well as after treatment with NC (2.5, 5.0, 7.5, and 10.0 μM) for 48 h." (PMID 33788424, 2021). "Later studies also proved this view and further found that cancer-IgG can also play the role of an oncogene through the AKT, FAK, SOX2, and other signaling pathways in cancer cells." (PMID 34760705, 2021). "It is worth noting that LR004-VC-MMAE also downregulated cancer stemness-related genes, such as Oct4, Sox2, KLF4 and EpCAM." (PMID 34879870, 2021). "Sox2, Oct4, and Bmi1 are effective markers of cancer stem cells, because they play important roles in the growth of cancer stem cells and promote the malignant progression of tumors." (PMID 33788424, 2021). "The results demonstrate that violacein markedly suppressed the expression of CD133, Sox2, Oct4, and Nanog in Huh7 cancer stem-like cells." (PMID 34639072, 2021). "Together with the information presented above, these results indicate the existence of repressive, cross-regulatory interactions between SOX2, p21CIP1 and p27KIP1 that play important roles in cancer cells." (PMID 33805518, 2021). "Similar findings in proteins associated with cancer stemness have been published for AF4/FMR2 family member 4 (AFF4) and sex-determining region Y box2 (SOX2) in head and neck squamous cell carcinoma." (PMID 34312483, 2021). "Because Ki-67 and Sox-2 high expression is conducive to cancer metastasis, the cells highly expressed Ki-67 and Sox-2 in this case, and the prognosis of this case appeared poor." (PMID 34712723, 2021). "Regulating Sox2 suppresses the metastasis and growth of many cancer cells, so Sox2 is a potential target in cancer treatment." (PMID 33738260, 2021).
cancer (continued). "Further, cells positive for pluripotency, stemness and cancer stem cell niche markers SOX2, ALDH1A1, EPCAM, LGR5 and PORCN were also significantly expanded in Ahr-deficient lesions along the time window analyzed." (PMID 34439225, 2021). "There are some explanations for the contradictory results regarding the tumorigenic role of SOX2 in different cancers." (PMID 34436030, 2021). "SOX2 is a transcription factor postulated to promote cancer development and progression, and increased SOX2-expression has been observed in SCC, and precursors of SCC, of the cervix, vulva, esophagus, and oral cavity." (PMID 33918187, 2021). "Although it has high relevance to cancer progression and drug resistance, directly targeting SOX-2 had been difficult because transcription factors are regarded as undruggable targets." (PMID 34163000, 2021). "The connection between cell stemness and SBSN expression suggested previously is supported by the identification of SOX2, a stem cell factor commonly upregulated in cancer, as a regulator of SBSN expression in oesophageal squamous cell carcinoma (ESCC)." (PMID 33477529, 2021). "To confirm the tumorsphere formation, we isolated RNA from sphere and analyzed cancer stem cell markers, SOX2, OCT4, and NANOG using real-time PCR." (PMID 33925065, 2021). "SOX2 expression has been associated with increased CRC metastasis, increased CRC cell migration, and cancer stem-like properties in CRC." (PMID 34503224, 2021). "LR004-VC-MMAE also inhibited the activation of EGFR signaling and the expression of cancer stemness marker genes such as Oct4, Sox2, KLF4 and EpCAM." (PMID 34879870, 2021). "MLN4924-mediated Sox2 downregulation has been shown to suppress stem cell properties and to exert broad anti-cancer effects both in in vitro and in vivo models." (PMID 34195082, 2021). "SOX2 promotes cancer cell traits such as proliferation, EMT, migration, invasion, and metastasis, as well as resistance to apoptosis and therapies." (PMID 34809669, 2021). "Previous work has shown that Sox2 marks and maintains cancer stem cells in a variety of cancers, including tumors of epithelial, neural and mesenchymal origin." (PMID 34201496, 2021). "Specifically, the DNA repair genes like RAD51B and RAD18, cancer stem cell marker SOX2 and antiapoptotic genes were significantly up regulated in radiation resistant cells." (PMID 34762666, 2021). "The copy number profiles agree with the GISTIC results, showing cancer type-specific amplifications of the noncoding regions 3′ and 5′ to SOX2." (PMID 34880227, 2021). "A recent report suggests SOX2 as an essential TF for the self-renewal capacity of cancer stem cells implicating SOX2 as an oncogenic TF." (PMID 33613844, 2021). "Understanding how SOX2, a major driver of cancer stem cells, is regulated in cancer cells is relevant to tackle tumorigenesis." (PMID 33805518, 2021). "Amplification of SOX2 was common, as has previously been reported in several cancer forms, including HGSC." (PMID 34069138, 2021). "To examine the effect of SMF on cancer stemness in mice, we used immunohistochemistry staining to detect the expressions of C-myc, Sox2, and CD44." (PMID 34917231, 2021). "The dysregulated OCT4/SOX2 complex has been detected in various human malignant tumors, and thus, SOX2 plays a critical role in cancer development." (PMID 33789601, 2021). "In line with our results, several studies reported that SOX2 overexpression was correlated with poor prognosis in various cancers." (PMID 34436030, 2021). "The gene expression of CRC cancer stem cell markers, including SOX2, OCT4, NANOG, KLF4, ALDH1A1, and CD44, were all highly expressed in CARMA3-overexpressed cells compared to control cells." (PMID 34885061, 2021). "Transcription factors Sox2 and Oct4 are essential in maintaining the pluripotency of embryonic stem cells and conferring stemness in cancer stem-like (CSL) cells." (PMID 34287231, 2021).
cancer (continued). "SOX2 is also expressed in many types of cancer cells and regulates their proliferation, survival, differentiation, and tolerance to anti-cancer drugs." (PMID 33795719, 2021). "While the expression of Sox2 and Oct4 is normally restricted to embryonic stem cells, the aberrant expression of these two proteins has been found in various types of cancer." (PMID 34287231, 2021). "SLUG and TWIST1, master EMT-inducing transcription factors, made essential contributions to TMPRSS4-mediated cancer stem cell (CSC) features through upregulation of SOX2." (PMID 34809669, 2021). "HHEX caused a repression of a series of neural stemness genes or/and genes promoting cancer, Sox1, Sox2, Myc, Cdh2, Vim, Hes1, Zic1, Pax6, Ezh2, and Lsd1." (PMID 34595169, 2021). "In this study, violacein noticeably reduced the expression levels of CD133, Sox2, Oct4, and Nanog in Huh7 cancer stem-like cells." (PMID 34639072, 2021). "SOX2 is a transcription factor that regulates cancer stemness in a variety of cancers (liver cancer, colorectal cancer, breast cancer, gastrointestinal cancer, and pancreatic cancer)." (PMID 33669204, 2021). "By lowering MSI1 expression in spheroid culture, cancer stem cell proliferation is inhibited, as is the expression of Notch1 and cancer stem cell markers such as Oct4, Sox2, and c-Myc." (PMID 34587981, 2021). "Analysis of the tumors from this GEM model indicated that the tumors were hierarchically organized with a small population (<5%) of SOX2-positive (SOX2+) cancer stem cells that self-renewed, yet proliferated infrequently." (PMID 35054230, 2021). "SOX2 is ectopically expressed in various cancers and is a prognostic marker and a promising therapeutic target in cancer." (PMID 33456560, 2021). "METTL3 acts on the reader IGF2BP2, and IGF2BP2 directly binds to a specific m6A site of in SOX2 CDS and controls the half-life of SOX2 mRNA by relying on m6A modification to produce cancer-promoting effects." (PMID 34246319, 2021). "SOX2 not only plays a vital role in cancer cell stemness, but also in invasion and metastatic potential." (PMID 33613844, 2021). "The transcriptional regulator Sox2 has been shown to be directly regulated in developmental and cancer contexts by Six1, Six2, Six3, and Six6 to further promote stem/progenitor cell phenotypes." (PMID 34490256, 2021). "The expression of HeyL, together with the stemness-associated genes SOX2, OCT4, KLF4, and CD44, was significantly increased in PCSCs compared with the corresponding bulk cancer cells." (PMID 35096586, 2021). "Meanwhile, Sox-2 and Oct-4 are well known to be involved in maintaining the stemness, cancer progression, and the resistance towards cancer therapies of cancer cells." (PMID 34885925, 2021). "NE tumors with SOX2 expression are therefore likely the exception to the here-described selection for silencing of SRRM4 in cancer." (PMID 33621242, 2021). "The stemness-associated markers OCT4, NANOG, SOX2, KLF4 and c-MYC are expressed in numerous cancer types suggesting the presence of cancer stem cells (CSCs)." (PMID 34685477, 2021). "Several studies noted the aberrant SOX2 expression in different types of benign and malignant neoplasms." (PMID 34261507, 2021). "Enrichment of cancer stem‐like cells was confirmed by investigating the expression of SOX2, KLF4, NANOG and OCT4 key stemness genes using real‐time PCR." (PMID 33634564, 2021). "13R,20-diHDHA reduced the populations of CD44high/CD24low and aldehyde dehydrogenase (ALDH)-positive cells and the expression levels of the cancer stemness-related self-renewal genes, Nanog, Sox2, Oct4, c-Myc, and CD44." (PMID 33804152, 2021). "Studies have shown that SOX2 overexpression leads to increase cell proliferation and promotes invasion, migration, and metastasis in various human cancers." (PMID 33339129, 2020).
cancer (continued). "For most human cancers, SOX2 acts as an oncoprotein by activating several proliferative and antiapoptotic signal cascades to promote tumorigenesis, metastasis, and drug resistance." (PMID 32728033, 2020). "The in vivo administration of EGCG also shows the reduction of cancer growth and the levels of stemness factors, such as SRY-box transcription factor 2 (SOX2), Octamer-binding protein 4 (OCT4), and Nanog homeobox (NANOG)." (PMID 33066509, 2020). "Our study shows that FGFRs play important roles in SOX2 protein stabilization and nuclear localization in cancer stemness regulation." (PMID 32457900, 2020). "Analysis revealed that genes associated with cancer stem cells, such as POU5F1 (OCT4), SOX2, NANOG, BMI1, BMP2, CD44, SOX9, and ALDH1 were markedly upregulated in enzalutamide resistant cells." (PMID 33339129, 2020). "At 1 year post-diagnosis, 44% of the cats in the Sox2– group, and 58% of the cats in the Sox2+ group had died from cancer." (PMID 33553286, 2020). "SOX2 staining was predominantly found in the nucleus of cancer cells, consistent with its biological role as a transcription factor." (PMID 32365581, 2020). "Recent studies from our and other groups have shown an interplay between the transcription factor GLI1, the final effector of the Hedgehog (HH) pathway, and the pluripotency transcription factor SOX2 in several types of cancer including melanoma." (PMID 33203881, 2020). "The stem cell markers c-MYC and SOX2 play important roles in the regulation of differentiation and also regulate cancer cell growth and chemotherapy resistance." (PMID 33089188, 2020). "Mechanistically, we found that TM4SF1 promotes cell metastasis and maintains the phenotypes of EMT and cancer stemness via the Wnt/β-catenin/c-Myc/SOX2 pathway in CRC." (PMID 33153498, 2020). "In general, SOX2 blocks cell cycle upon differentiation signals to maintain the stemness and accelerates cell cycle upon growth signals for cancer cell proliferation." (PMID 32728033, 2020). "A recent study reported that the clinical expression of the pluripotent factors OCT4, SOX2, and NANOG (OSN) in cancer patients was associated with treatment resistance of lethal cancers." (PMID 32493501, 2020). "With respect to the effect of ibuprofen on cancer cell stemness properties, we found that the immunocytochemical staining of SOX2 and OCT4 stemness markers decreases in the cisplatin/ibuprofen-treated groups versus cisplatin/DMSO control." (PMID 32528119, 2020). "Taken together, various lines of evidence elaborated in mouse models, human cancer cells, reprogramming settings, and clinical datasets, exemplify a functional cooperativity of SOX2 with the PI3K/AKT signaling pathway." (PMID 31477842, 2020). "SOX2 is a marker for cancer stem cell in head and neck cancer, and is a prognostic marker with unfavorable outcome." (PMID 33344262, 2020). "This includes OCT4 protein expression, POU5F1, NANOG and SOX2 gene expression in cell lines or cancer-initiating cells." (PMID 32664372, 2020). "LIPH silencing decreased the stem‐like cancer cell population, down‐regulating stem‐like cell markers (Sox2 and Oct‐4) in TNBC cells." (PMID 32618099, 2020). "Knockdown studies have demonstrated that SOX2 is required for growth of cells from over 20 different human cancers." (PMID 32998722, 2020). "SOX2+ cancer cells have been shown to be quiescent, potentially conferring treatment resistance, are able to avoid immune recognition and can also form metastatic niches." (PMID 32365581, 2020). "All these facts indicate a critical role of SOX2 in initiation, progression, and sustenance of cancer, signifying the importance of exosomal SOX2 DNA analysis." (PMID 32092088, 2020). "In most types of cancers, SOX2 acts as an oncogenic transcriptional factor and is elevated in malignant tissue as compared to normal tissue." (PMID 33489519, 2020).
cancer (continued). "Although PI3K/AKT inhibitors have been widely used to treat cancers, we provide a novel mechanism of them for promoting CSCs differentiation by destabilizing SOX2." (PMID 32194860, 2020). "Sex-determining region Y-box2 (SOX2) is a stem cell transcription factor essential for maintaining the properties of cancer stem cell (CSC)." (PMID 32144236, 2020). "Previous research reported that lysine-specific histone demethylase 1 (LSD1) maintains cancer stemness through up-regulating stemness markers SOX2 and OCT4." (PMID 32520208, 2020). "Transcription factor sex-determining region Y-box 2 (SOX2) involves in the maintenance of cancer stem cells." (PMID 32104175, 2020). "Amplification of SOX2 is common in different cancer types, which adversely effects cancer cell physiology via altering stem cell signaling pathways." (PMID 33344262, 2020). "Our findings highlight the crucial relationship between CAFs and PCAT-1 which triggers a CD133/SOX2-related stem cell phenotype and acquisition of cancer cell chemoresistance." (PMID 32754302, 2020). "Treatment with α-mangostin, Man-3DG, and Man-6DG markedly decreased the expression levels of cancer stemness regulators, including Nanog, Oct4, Sox2, CD44, and CD133, in the 3D tumorsphere-cultured Hep3B cells." (PMID 32516967, 2020). "Given the critical role of SOX2 in the initiation and progression of tumorigenesis, it is not surprising that SOX2 dysregulation is frequently occurring in human cancer tissues." (PMID 32728033, 2020). "For example, as the stemness regulator master, sox2 maintains cancer cell stemness by antagonizing the Hippo pathway." (PMID 32612672, 2020). "Of them, a cancer‐related miRNA, hsa‐miR‐340‐5p, showed a higher binding affinity with SOX2 in network regulation mapping, which was also found to be markedly downregulated under qPCR analysis." (PMID 32130794, 2020). "SOX2 overexpression promotes cancer progression by accelerating cell proliferation, colony formation, migration, invasion, and sphere formation." (PMID 31748974, 2020). "SOX2 activation has proved instrumental for the plastic acquisition of aberrant stemness properties in cancer cells." (PMID 32191225, 2020). "GSCs express both embryonic and neural progenitor cancer stem cell markers, including SOX2, nestin, and CD133." (PMID 32430842, 2020). "Collectively, SOX2 can also induce the occurrence of angiogenesis and VM, implying its diverse function in cancer progression." (PMID 32144236, 2020). "Despite multiple studies published so far exploring the role of SOX2 in cancer, its impact on disease outcome remains controversial." (PMID 32635524, 2020). "Recently, an experimental DNA vaccine has been developed against sternness-specific marker Sox2 and an antitumor effect also has been seen after immunization against murine lung TC-1/B7 cancer cells expressing oncogenic Sox2." (PMID 32211043, 2020). "A common target gene of PRMTs and GLI, SOX2, is a one of the factors that reprogram differentiated cancer cells into CSCs." (PMID 32859041, 2020). "Our study, therefore, provides a novel mechanism by which MLN4924 regulates cancer stem cell property and overcomes tamoxifen resistance with potential therapeutic application in targeting human cancers with SOX2 overexpression." (PMID 31748974, 2020). "To investigate how GATA5 mechanistically stimulated Paclitaxel to suppress malignantbehaviors of HCC cells, we analyzed expression of the cancer stem cell reprogramminggenes, Nanog, EpCAM, c-Myc and Sox2 in the cells by Western blotting." (PMID 32779438, 2020). "SOX2 expression in these cells is therefore necessary to maintain stemness and can be a promising target for the treatment of SOX2-positive cancers." (PMID 32457900, 2020). "Several preclinical studies in a range of cancer models have indicated that SOX2+ cancer cells exhibit characteristic CSC properties." (PMID 32365581, 2020).